MYCN (MYCN proto-oncogene, bHLH transcription factor)
Diseases named in the same sentence as MYCN in open-access papers (continued):
Sharing a sentence is not in itself a finding about the gene and the disease.
neuroblastoma (continued). "MYCN is a transcription factor that is expressed during the development of the neural crest and its dysregulation plays a major role in the pathogenesis of pediatric cancers such as neuroblastoma, medulloblastoma and rhabdomyosarcoma." (PMID 21731748, 2011). "Therefore, both stage and MYCN amplification seem to affect the alternative splicing patterns in neuroblastoma." (PMID 21501490, 2011). "Similarly, miR-9, which is positively regulated by MYCN in human neuroblastoma, was also significantly up-regulated in the mouse tumors." (PMID 22164278, 2011). "MYCN amplified neuroblastoma is the most aggressive disease subtype." (PMID 21501490, 2011). "This study also showed that treatment of MYCN-amplified and therapy-resistant neuroblastomas with an oligonucleotide designed to block the action of miR-17-5p, a miR-17-5p antagomir, abolishes the p21 and BIM upregulation, inhibits cell cycle progression and promotes apoptosis." (PMID 24212967, 2011). "The high-risk group comprises all MYCN-amplified neuroblastoma regardless of stage and age of the child, and non-MYCN-amplified stage 4 neuroblastoma for children of age ⩾18 months." (PMID 21970883, 2011). "MYCN oncogene amplification and consequent N-Myc mRNA and protein over-expression, are seen as a clonal feature in a quarter of tumors, and correlate with poorer prognosis in patients with neuroblastoma." (PMID 21698133, 2011). "Interestingly, 12q24.31 gains and MYCN amplifications were present in different subsets of neuroblastomas." (PMID 20444257, 2010). "Either MYCN amplification or 12q24.31 gain was present in 64% of all neuroblastomas." (PMID 20444257, 2010). "We then speculated that B-MYB could be involved in the regulation of MYCN in the context of neuroblastoma." (PMID 21304178, 2010). "Clinical and molecular risk factors which correlate with prognosis include age at diagnosis, stage, histology, chromosomal aberrations, and amplification of the N-myc proto-oncogene (MYCN), which is the most typical genetic feature of advanced-stage neuroblastoma." (PMID 20624283, 2010). "To investigate whether a reciprocal feedback loop is operating in human neuroblastoma cells with amplification of MYCN, we infected IMR-32 cells with B-MYB, or scrambled, shRNA lentivirus." (PMID 21304178, 2010). "Moreover, although the NGP cell line was shown to contain both MYCN and 12q24.31 amplifications, we found only one neuroblastoma in the tissue array analysis with both genetic modifications." (PMID 20444257, 2010). "A computational approach using a priori biological knowledge to analyze the data of clinical neuroblastoma studies was applied successfully to the analysis of MYCN transcriptional targets whose over-expression contributes to the prediction of relapses and death from neuroblastoma." (PMID 20624283, 2010). "What do we know about transcriptional regulation of MYCN in neuroblastoma?" (PMID 21304174, 2010). "As an inhibitor of AKT2, miR-184 could be of potential benefit in miRNA mediated therapeutics of MYCN amplified neuroblastoma and other forms of cancer." (PMID 20409325, 2010). "In the light of this study, we asked whether MYCN and B-MYB were functionally linked in neuroblastoma and, if so, what are the functional consequences." (PMID 21304178, 2010). "It is well known that MYCN amplification strongly correlates with adverse outcome in neuroblastoma." (PMID 20380745, 2010). "Nevertheless, HMGA1 expression is influenced by MYCN status in neuroblastoma cells: this gene is significantly more expressed in MYCN-amplified neuroblastomas and it might be also activated by c-MYC or other transcription factors." (PMID 20459794, 2010). "In principle, MYCN could be an ideal target for therapy: it is aberrantly overexpressed in neuroblastoma and only marginally present in normal tissues." (PMID 21304178, 2010).
neuroblastoma (continued). "Thus, we conclude that addiction of neuroblastoma cells to B-MYB is contingent on the presence of the MYCN amplicon and reflects the crucial role of B-MYB in its transcriptional regulation." (PMID 21304178, 2010). "The 11q13 amplicon is generally located at the same chromosome region of the single-copy genes involved (CCND1, etc.); other amplifications, such as those involving MYCN in neuroblastomas, are inserted in several places in the genome other than chromosome 2, where MYCN gene is mapped." (PMID 20540739, 2010). "Nevertheless, whether MYCN expression is truly predictive of neuroblastoma outcome remains controversial." (PMID 20380745, 2010). "If significant transcriptional regulation of the MYCN amplicon in neuroblastoma could be characterized and exploited, these could result in novel strategies to target this deadly disease." (PMID 21304174, 2010). "Blunting B-MYB expression by RNA interference causes reduced proliferation of MYCN amplified, but not MYCN-non amplified, neuroblastoma cell lines, indicating that tumour cells are addicted to B-MYB in a MYCN dependent manner." (PMID 21304178, 2010). "One of many down-stream MYCN targets is miR-184, which is either directly or indirectly repressed by this transcription factor, possibly due to its pro-apoptotic effects when ectopically over-expressed in neuroblastoma cells." (PMID 20409325, 2010). "Whether the effects of the 12q24.31 gain and MYCN amplification represent actually two alternative routes in neuroblastoma progression, remains, however, to be investigated further in separate studies." (PMID 20444257, 2010). "Neuroblastoma cells (NBs) that carry an amplified MYCN gene are extremely malignant." (PMID 19615087, 2009). "A murine model of neuroblastoma has been established by targeted expression of the human MYCN oncogene in neuroectodermal cells under the control of rat tyrosine hydroxylase promoter (TH-MYCN)." (PMID 19730731, 2009). "Currently, patients with MYCN amplified neuroblastoma tumors have less than a 30% chance of 5-year survival, thus identification of downstream MYCN targets is critically important for the development of alternative treatment regimens and improving patient survival." (PMID 19997598, 2009). "Given the importance of MYCN amplification in neuroblastoma, we initially identified miRNAs that were differentially expressed between MNA versus non-MNA tumors using the Wilcoxon Rank test based p-values corrected for multiple comparisons (using the training set of tumors, n = 96)." (PMID 19924232, 2009). "Use of transgenic mice expressing the human MYCN oncogene has provided definitive evidence for the role of MYCN in neuroblastoma tumorigenesis, recapitulating several biological and histological aspects of clinical neuroblastomas." (PMID 19730731, 2009). "The aim of this study was primarily to characterize tumor spread in an orthotopic, metastatic model for aggressive, MYCN-amplified neuroblastoma and secondarily to study the effects of daily administration of the chemotherapeutic agent CHS 828 on tumor angiogenesis, tumor growth, and spread." (PMID 19284605, 2009). "Conversely, antagomir-17-5p treatment may be beneficial in MYCN-amplified neuroblastoma, also in view of evidence suggesting that systemic antagomir treatment is not coupled with significant toxicity." (PMID 18493594, 2008). "To determine whether miR-17-5p mediates tumorigenesis in MYCN-amplified neuroblastoma cells, we evaluated the effect of miR-17-5p knockdown in LAN-5 cell line, which expresses miR-17-5p at elevated level." (PMID 18493594, 2008). "Of greatest concern in neuroblastoma is the rare patient who despite a favorable clinical profile and no MYCN amplification progresses to high-risk disease." (PMID 21892309, 2008).
neuroblastoma (continued). "Furthermore, by clarifying the statistical principles of MYCN amplicon segregation, we have now acquired a precise standard against which the effects of potential anti-neuroblastoma drugs acting through MYCN amplicon elimination can be compared." (PMID 18769732, 2008). "Based on the relative expression of MYCN and c-MYC in neuroblastoma subtypes, we propose that elevated MYCN activity in stage 4s-NA tumors induces only a restricted set of MYCN/c-MYC target genes, whereas elevated c-MYC activity in stage 4-NA tumors induces a larger set of MYCN/c-MYC target genes." (PMID 18851746, 2008). "Here, we investigated whether there was a correlation between up-regulated glycolytic capabilities and the level of MYCN expression of three cell lines derived from patients with neuroblastoma who subsequently died of the disease." (PMID 18789162, 2008). "Some miRNAs, including miR-9, miR-125 and miR-34a control neuroblastoma cell proliferation in vitro, but their function has not been linked to neuroblastoma carrying MYCN amplification." (PMID 18493594, 2008). "MYCN is an oncogene that is critical in the pathogenesis of neuroblastoma." (PMID 18789162, 2008). "We verified MYCN amplification in ten neuroblastoma cell lines by Southern hybridization." (PMID 17601344, 2007). "However, at present only two genes, namely MYCN and PHOX2B, have been directly linked to neuroblastoma development, although their exact role in oncogenesis is still unclear." (PMID 16989664, 2006). "MYCN amplification was strongly correlated with a poor prognosis in infantile neuroblastoma cases." (PMID 16670717, 2006). "In addition to the well known group of high stage neuroblastomas with MYCN amplification and 1p-deletion, a second genetic subgroup of aggressive neuroblastomas has been delineated." (PMID 16000168, 2005). "A number of factors that correlate with the response to treatment and outcome of patients with neuroblastoma have been identified, including patient age, stage, histology, MYCN amplification, DNA ploidy, 1p deletions, 17q gain, TRKA expression and CD44 cell-surface expression." (PMID 11953858, 2002). "In order to identify additional molecular markers with prognostic potential in non-MYCN-amplified neuroblastomas, we looked for a correlation between clinical outcome and loss of heterozygosity (LOH) on four chromosomes that frequently show alteration in neuroblastoma (chromosomes 3, 4, 11 and 14)." (PMID 11506492, 2001). "However, the data on the incidence of ATRX mutation and clinical significance in MYCN non-amplified neuroblastoma is limited." (PMID 40286729, 2025). "This review summarizes the current research progress of therapeutics that indirectly target MYCN for the treatment of neuroblastomato provide new ideas for the treatment of MNA-NB and other MYCN-amplified tumors." (PMID 41244073, 2025). "A previous study has shown that ADC histogram features can distinguish between MYCN-amplified and non-amplified neuroblastomas, though the underlying biological mechanisms remain unclear." (PMID 41228227, 2025). "To investigate the cellular and molecular mechanisms underlying the fate determination of neuroblastoma cells in Th-MYCN+/− mice, we performed scRNA-seq of SMG tissues from 3-week-old wild-type (WT, n = 1), 3-week-old Th-MYCN+/− (n = 10), and 6-week-old Th-MYCN+/− mice (n = 1)." (PMID 40580553, 2025). "MYCN amplification is known to predict poor prognosis in neuroblastoma (NB) patients, and our subgroup analysis revealed that the NB group with MYCN amplification had higher scores." (PMID 40718780, 2025). "The efforts associated with our approach are justified to enable sensitive detection of TERT rearrangements in this molecular high-risk subgroup of neuroblastoma, which does not overlap with cases harboring MYCN amplifications and includes both high-risk and very high–risk disease." (PMID 39760332, 2025). "Consequently, STM2457 downregulates MYCN to achieve an anti-tumor effect in neuroblastoma." (PMID 40823087, 2025).
neuroblastoma (continued). "Besides, KLHL37 knockdown induced significant apoptosis of MYCN-amplified neuroblastoma cells." (PMID 40493396, 2025). "Thereby, the data raise the possibility that topoisomerase inhibitors (topotecan or irinotecan) might be clinically useful in neuroblastoma MYCN amplified or MYCN non-amplified patients with ATRX loss-of-function, as was observed in patient NB1." (PMID 40286729, 2025). "Furthermore, the effect of ATRX nonsense mutations in MYCN non-amplified neuroblastoma has not been extensively studied in patients." (PMID 40286729, 2025). "Here, we wanted to elucidate the role that PRMT5, E2F1 and MYCN may take on in neuroblastoma." (PMID 39021294, 2025). "In addition, high MIF and MDK expression was significantly associated with inferior event-free and overall survival of neuroblastoma patients, which was independent of MYCN amplification." (PMID 39908652, 2025). "A 6-year-old female was diagnosed with INSS high-risk stage 4 neuroblastoma with primary adrenal mass and bone metastases that included skullcap, lymph nodes, and the bone marrow, unfavorable histology, MYCN non-amplified, and ALK with no detectable abnormal mutations." (PMID 40286729, 2025). "The International Neuroblastoma Risk Group Staging System (INRGSS) defines HR-NB by the presence of metastatic disease (stage M) in patients diagnosed above 12 months of age; or by the amplification of MYCN (MNA), in unresectable or metastatic tumors (stage L2, Ms and M)." (PMID 39998749, 2025). "In recent years, the scientific community has conducted research on ferroptosis-related gene-targeted therapies for MYCN-amplified neuroblastoma (NB), achieving significant progress." (PMID 40108662, 2025). "Additionally, we found that KLHL37 also had a regulatory effect on C-Myc, and we suspect that this effect may contribute to the carcinogenic potential of KLHL37 in non-MYCN-amplified neuroblastoma as well as other tumors, which merits further investigation." (PMID 40493396, 2025). "Nevertheless, there is no direct evidence demonstrating that MYCN causes neuroblastoma." (PMID 39720601, 2025). "We performed ASCL1 ChIP-seq in another MYCN-amplified neuroblastoma cell line (IMR-32) and a non MYCN-amplified cell line (SH-SY5Y), showing that ASCL1 binding at loci associated with both proliferative and neuronal genes is a general feature of ASCL1 functionality in neuroblastoma." (PMID 40452575, 2025). "However, GD2 expression levels in TH-MYCN (a transgenic neuroblastoma model driven by tyrosine hydroxylase promoter–driven MYCN overexpression) NBs were previously considered too low for targeting, resulting in the inadequate use of this model for GD2-targeted therapy studies." (PMID 41244073, 2025). "Notably, in high-risk neuroblastoma cases lacking MYCN amplification, c-MYC overexpression can serve as a functional driver, conferring similarly poor clinical outcomes." (PMID 41002386, 2025). "Since this is the case, singular treatment indirectly targeting MYCN via AURKA may not be a viable option for NEPC treatment; however, an in vivo neuroblastoma study has shown a synergistic inhibition of tumour growth and MYCN expression with a BRD4 inhibitor (I-BET151) and alisertib." (PMID 39682746, 2024). "Therefore, it is possible that neuroblastoma with MYCN amplification may contain less extracellular matrix, which could be related to the sensitivity of tumor cells to chemotherapeutic agents." (PMID 38959634, 2024). "However, molecular methods, such as microarrays, have strong limitations when analyzing MYCN amplification and other genetic changes in neuroblastoma because molecular methods are based on DNA from a mixture of cells and therefore only provide an average result for a particular tumor." (PMID 39049899, 2024). "The study sought to repurpose ceftriaxone for MYCN‐amplified retinoblastoma (RB) and neuroblastoma (NB) treatment due to its observed capability to reduce MYCN‐driven RB subtype volume." (PMID 37975412, 2024).
neuroblastoma (continued). "Additionally, the kinase is the main factor responsible for MYCN stability in neuroblastoma." (PMID 38495105, 2024). "It is important to note, however, that AhR antagonism may not benefit all type of cancers as, as noted in the sections above, in a subset of diseases AhR has been shown to act as a tumor suppressor (i.e. ER+ breast cancer, androgen-sensitive prostate cancer, non-MYCN-amplified neuroblastoma)." (PMID 38807762, 2024). "In addition, among the six high-risk neuroblastoma tumors examined, we observed a difference in CD47 staining in high-risk neuroblastoma with MYCN amplification vs. those without MYCN amplification." (PMID 38920727, 2024). "However, this may be explained by stage 4 neuroblastoma complicated by MYCN, which requires further investigation." (PMID 38558810, 2024). "Complex heterogeneity exists within the tumor subpopulation of neuroblastoma, with prognostic factors for survival including age at diagnosis, tumor site, tumor grade, histology, and amplification of the v-myc avian myelocytomatosis viral oncogene neuroblastoma-derived homolog (MYCN) gene." (PMID 38214542, 2024). "In addition to these two main genetic markers, a number of segmental aberrations involving different chromosomes have also been described that, in addition to MYCN amplification, have a strong effect on the development of neuroblastoma, making it more aggressive and resistant to treatment." (PMID 39049899, 2024). "Similarly, lncNB1 is highly overexpressed in MYCN-amplified neuroblastoma." (PMID 38891878, 2024). "In patients suffering from neuroblastoma, eccDNA-driven chromosomal rearrangements of the MYCN oncogene have been associated with poor prognosis and overall survival compared to patients without the eccDNA-derived remodeling of MYCN." (PMID 39202666, 2024). "Neuroblastoma (NB) patients with amplified MYCN often face a grim prognosis and are resistant to existing therapies, yet MYCN protein is considered undruggable." (PMID 38745192, 2024). "Therefore, induction of MYCN at tNCCs generates tumors resembling neuroblastoma." (PMID 38451815, 2024). "Thus, this redundancy may explain why MYCN-amplified neuroblastoma depends on TADA2B, which is required for full KAT activity." (PMID 38820154, 2024). "Case 3 was a child who presented at 17 months of age and was diagnosed with MYCN-amplified, undifferentiated neuroblastoma (NB)." (PMID 38501975, 2024). "Moreover, T follicular helper cells (TFHs) showed a significant positive association with survival in high-risk neuroblastoma without MYCN amplification." (PMID 38542199, 2024). "In addition, the majority of TERT-positive neuroblastoma cells are MYCN-amplified." (PMID 38837897, 2024). "However, we do note that the observed MYCN-dependency may reflect the initial chemosensitivity that is exhibited in MYCN-amplified neuroblastomas." (PMID 38049564, 2024). "Simulations based on the multicellular model alone revealed how a MYCN-amplified clone is non-linearly related to the other clones (with other mutations) commonly found in a neuroblastoma tumour, its gene expression profile, the tumour’s clonal composition, and its microenvironment." (PMID 39715281, 2024). "In the case of solid tumours, our group previously demonstrated that neuroblastoma cells over-expressing the MYCN oncogene are highly susceptible to loss of PRMT5, prompting this preclinical assessment of the selective PRMT5 inhibitors GSK3203591 and GSK3326593 in neuroblastoma." (PMID 39313128, 2024). "In neuroblastoma (NB), MYCN-induced upregulation of the H3K9 methyltransferases G9a and GLP as well as EZH2 can also inhibit IFN-γ-induced expression of CXCL9 and CXCL10." (PMID 39080807, 2024). "Finally, we also demonstrated the formation of the alternative vasculature in the tissue by the identification of tumor-derived endothelial cells, which expressed both endothelial (CD31, cell membrane) and neuroblastoma (MYCN, nuclear) markers at the same time." (PMID 39872066, 2024).